LINC01515 (long independently transcribed non-coding RNA 1515)
Gene: Long non-coding RNA gene on chromosome 10 (65,570,338 to 65,880,289, forward strand). Ensembl gene ENSG00000228065.
Diseases named in the same sentence as LINC01515 in open-access papers:
LINC01515 is named in the same sentence as 2 diseases in open-access papers, as found by Europe PMC text mining. Sharing a sentence is not in itself a finding about the gene and the disease. The quoted sentences say what the papers report.
cancer (1 paper, 2022). A tumor composed of atypical neoplastic, often pleomorphic cells that invade other tissues. "As for the five key CRLs, numerous studies explored the LINC01515 function and HCG15 function in cancer." (PMID 36189204, 2022).
LINC01515 also shares sentences with these, for which no sentence is quoted: nasopharyngeal carcinoma (1 paper).